RAB31 (RAB31, member RAS oncogene family)
Diseases named in the same sentence as RAB31 in open-access papers (continued):
Sharing a sentence is not in itself a finding about the gene and the disease.
cancer (31 papers, 2011 to 2025). A tumor composed of atypical neoplastic, often pleomorphic cells that invade other tissues. "Increasing evidence indicates that miRNAs are involved in the progression of various tumors, and RAS-associated protein in the brain 31 (RAB31) is upregulated and promotes the progression of multiple malignant tumors." (PMID 36245214, 2022). "RAB31 can be detected in primary cancer-associated fibroblasts (CAFs) and paired normal fibroblasts." (PMID 33072555, 2020). "Several recent findings have helped to shed light on the possible underlying molecular pathways and mechanisms linking Rab31 to cancer." (PMID 25472813, 2015). "While Rab31 transcripts have also been found in cancer cells with the uPAR splice variant, and both are stabilized by HuR, it is unclear if the two have a causal or functional relationship." (PMID 25472813, 2015). "In the next section, we outline how Rab31 has been implicated in human cancers, and in the section after postulate the underlying mechanisms based on recent findings." (PMID 25472813, 2015). "In this review, we focus on a Rab5 subfamily member, Rab31, and its implicated role in cancer." (PMID 25472813, 2015). "Several expression profiling analyses have implicated Rab31 in human cancers." (PMID 25472813, 2015). "Rab31, a member of the Rab family of small GTPases, is believed to play a critical role in cancer initiation and progression." (PMID 41463174, 2025). "Recent studies have shown that Rab31 is an oncogene for numerous cancers, and Rab31 overexpression is related to cancer progression and poor prognosis." (PMID 36781842, 2023). "For example, in breast cancer, RAB31 was first identified as an independent prognostic factor and was later found to promote cancer progression and subsequent tamoxifen resistance in patients." (PMID 36245214, 2022). "The results of F-actin staining showed that F-actin expression and the pseudopod were all decreased with Rab31 knockdown; thus, the capability of metastasis of cancer cells was reduced." (PMID 34975321, 2022). "For the ESCRT independent pathway, both caveolin-1, flotillins, and Rab31 are ubiquitously overexpressed in cancer and promote cancer progression and chemoresistance by their function in controlling exosomes secretion." (PMID 36320056, 2022). "Our results showed that the expression of MMP2 and MMP9 was reduced with Rab31 knockdown, decreasing the capability of cancer cells to metastasize." (PMID 34975321, 2022). "Accumulating evidence has shown that Rab31 is widely involved in carcinogenesis and is related to the prognosis of various cancers." (PMID 34975321, 2022). "Specifically, single nucleotide variation (SNV) of OBSCN is the most frequently predicted gene alteration, while SNV of SEC16B, IRAK3, TNPO2, LIN9, and RAB31 constituted 9%, 5%, 5%, 4%, and 2% of genetic alterations in the TCGA cohort of the hub cancers." (PMID 34359748, 2021). "We found that in all the six cancer types analyzed, the expression levels of RAB31 and IRAK3 were positively correlated (all p-value < 0.05) with the gene expression profiles suggestive of infiltrations of all immune cell types analyzed (except B cells)." (PMID 34359748, 2021). "In tumor tissue, RAB31 expression in the cancer cells were generally low, while high expression was detected in the tumor stroma in a subgroup of samples." (PMID 33072555, 2020). "The expression of RAB31 was graded in both the cancer cells and tumor stromal compartment using a 3-tier scale: 1, no staining or weak staining; 2, moderate staining; 3, strong staining." (PMID 33072555, 2020). "Several genes involved in the GESGC have been reported to be associated with human cancer, including LOXL1, RAB31 and CBR1." (PMID 29957874, 2018). "The multifaceted action and influences of Rab31 in cancer is discussed in the light of its new interacting partners and pathways." (PMID 25472813, 2015).
cancer (continued). "We detected a weak to moderate cytoplasmic staining for rab31 and, occasionally, strong perinuclear and/or nuclear staining of cancer cells, whereas stromal cells were less frequently stained." (PMID 22920728, 2012). "Rab31 was significantly upregulated in both cancer cell lines." (PMID 41463174, 2025). "Because RAB31 plays an oncogenic role in a variety of human cancers, interventions targeting RAB31 expression may aid in inhibiting the progression of GC, and using RAB31-targeted miRNAs may provide a promising method for GC treatment." (PMID 36245214, 2022). "Many mutants of RAB31 have been detected in various types of human cancer, and we were very curious to test whether any RAB31 mutant may also induce this localization of EGFR to CD63-positive MVEs." (PMID 32958903, 2021). "In addition, our results suggested an association between high mRNA expression levels of RAB31 and SEC16B and the resistance of various cancer cell lines to 62 and 17 of small molecule anti-cancer drugs, respectively." (PMID 34359748, 2021). "While RAB31 may be expressed in both cancer cells and stromal cells, a higher percentage of stromal RAB31 expression was observed (56.12% vs. 35.71%)." (PMID 33072555, 2020). "The promotive effect of Rab31 on tumor progression has been reported in several kinds of cancers." (PMID 31083279, 2019). "Elevated Rab31 stabilizes MUC1-C levels in an auto-inductive loop that could lead to aberrant signalling and gene expression associated with cancer progression." (PMID 25472813, 2015). "However, still few data are available on rab31 expression in cancer in general or its impact on disease progression in particular ‒." (PMID 22920728, 2012). "Similarly, we queried the survival differences between the mRNA expression levels of each hub gene across the combined cohorts of the hub cancers and found that higher mRNA expression levels of RAB31, IRAK3, SEC16B, and LIN9 predicted shorter survival durations of the hub cancer cohorts." (PMID 34359748, 2021). "How this uPAR-CI-M6PR connection might relate to Rab31's role in cancer is yet unclear." (PMID 25472813, 2015). "RAB31, a RAB5 subfamily member, has been shown to be highly expressed in several cancers and is related to poor prognosis." (PMID 40226355, 2025). "This stable tRNA has a substantially increased efficiency necessary to support a pro‐cancer translation program including c‐Myc, BCL2, RAB31, JUNB and TRAF2." (PMID 37983928, 2023). "Subsequently, we knocked down RAB31 expression in SGC-7901 cells transfected with miR-378a-3p inhibitor and also observed that knockdown of RAB31 offset the cancer-promoting effect of the miR-378a-3p inhibitor." (PMID 36245214, 2022). "The high expression levels of RAB31, IRAK3, and TNPO2 were strongly correlated with gene expression profiles suggestive of dysfunctional T cell phenotypes in the six cancers." (PMID 34359748, 2021). "Notably, RAB31, IRAK3, OBSCN, LIN9, TNPO2, and SEC16B expressions were inversely correlated with the gene expression profiles suggestive of tumor purity of the hub cancer." (PMID 34359748, 2021). "The defined RAB31-FLOTs and RAB31-TBC1D2B machineries may provide a basis to potentially design therapeutic strategies for human diseases, such as cancer and neurodegenerative diseases." (PMID 32958903, 2021). "The strong correlation between the expression levels of RAB31, IRAK3, and OBSCN and the gene expression profile suggestive of CAF infiltrations strongly supported the tumor-promoting role of these genes in the hub cancers." (PMID 34359748, 2021). "Interestingly, high mRNA expression levels of RAB31 and SEC16B predicted cancer cell lines resistant to 62 and 17 small molecule anticancer drugs, respectively." (PMID 34359748, 2021). "In conclusion, our results suggest that ERCC6L may stimulates cancer cell proliferation by promoting cell cycle through a way of RAB31-MAPK-CDK2, and it could be a potential biomarker for cancer prognosis and target for cancer treatment." (PMID 28178669, 2017).
cancer (continued). "In addition, we also found that the presence of HDAC7 led to the upregulation of genes related to immune processes (IL16, FCGR2A, IRAK2, CD86 and CD40, among others) and cancer (RASSF4, RAB31, NEDD9 and RASSF2, among others)." (PMID 25675295, 2015). "Similarly, the expression levels of RAB31, IRAK3, and SEC16B were inversely correlated, while TNPO2 and LIN9 were positively correlated with gene expression profiles suggestive of MDSCs infiltration in the six cancer types." (PMID 34359748, 2021). "Besides, their further studies considered that ERCC6L might affect the cell cycle via RAB31-MAPF-CDK, so as to promote cancer cell proliferation." (PMID 30555514, 2018). "It is difficult at the moment to gauge quantitatively which one of the two apparently contrasting actions of Rab31, namely the auto-inductive loop that it is engaged with MUC1-C, or its effect on EGFR trafficking and signalling, would be a more important determinant of the cancer phenotype." (PMID 25472813, 2015). "Interestingly, expression of RAB31 in cancer cells was not correlated with survival." (PMID 33072555, 2020).
tumor (31 papers, 2012 to 2025). "We recently reported that elevated rab31 mRNA expression in primary tumor tissue is associated with poor prognosis of lymph node-negative breast cancer patients." (PMID 22920728, 2012). "With regard to the plasticity of tumor cells in reliance of rab31 expression, our results, however, demonstrate that rab31 expression is implicated in modulation of tumor-relevant biological processes." (PMID 22920728, 2012). "This may well explain also the clinical finding that elevated Rab31 levels, determined in primary tumor tissue, are associated with poor patient prognosis." (PMID 34906074, 2021). "By enhancing the stability of rab31 transcripts and regulation of their translation, HuR may cause higher rab31 levels in tumor cells." (PMID 22920728, 2012). "Moreover, loss of Rab31 suppresses tumor growth in a nude mouse model, while Rab31 deficiency through glioma-associated oncogene homolog 1 (GLI1) suppresses cell motility, promotes apoptosis, and regulates the expression levels of cell cycle and apoptotic proteins in vitro." (PMID 38695990, 2024). "In vivo experiments further validated that Cx43 overexpression promotes tumor growth and upregulates Rab31 and autophagy-related proteins." (PMID 41463174, 2025). "In tumor tissues, Cx43 overexpression upregulates Rab31 expression, and various assays were employed to examine downstream molecules regulated by Cx43." (PMID 41463174, 2025). "Rab31 knockdown yields the equivalent effects as cisplatin treatment for inhibiting the tumor growth compared to the control." (PMID 36781842, 2023). "Accumulating evidence reveals that dysregulation of Rab31 is involved in tumor development and progression." (PMID 36781842, 2023). "Lastly, we extended to examine the influence of Rab31 expression levels on tumor growth in vivo by employing a patient-derived xenograft (PDX) model in nude mice using human STAD tissue." (PMID 36781842, 2023). "The present study also demonstrates that Rab31 knockdown inhibited tumor growth in mice STAD models." (PMID 36781842, 2023). "Rab31 knockdown inhibited the colony formation in all three STAD cell lines tested, while Rab31 overexpression enhanced the formation of tumor colonies (top)." (PMID 36781842, 2023). "Simultaneous treatment with cisplatin and Rab31 knockdown significantly reduced tumor cell proliferation, suggesting that Rab31 is a potential therapeutic target that can be paired with cisplatin treatment for STAD." (PMID 36781842, 2023). "We showed that Rab31 knockdown along with cisplatin significantly inhibited tumor growth compared with the group treated with cisplatin alone." (PMID 36781842, 2023). "Reduced Rab31 expression induces tumor cell apoptosis and increases cisplatin sensitivity in STAD cells; Rab31 overexpression yielded the opposite result." (PMID 36781842, 2023). "As a member of the Ras oncogene family, the high expression of RAB31 has always been thought to be closely related to the enhancement of tumour invasiveness, the decrease in apoptosis and the poor prognosis of patients." (PMID 35322540, 2022). "Overall, our findings demonstrated that miR-378a-3p, which directly targets RAB31, exerts a tumor-suppressive effect in GC." (PMID 36245214, 2022). "In summary, our findings indicated that miR-378a-3p functions as a tumor suppressor in GC by directly targeting RAB31 and inhibiting GLI1/2 in the Hedgehog pathway." (PMID 36245214, 2022). "The prioritization of the hub genes in the gene expression profiles suggestive of tumor immune evasion and immunotherapy response occurs in the order of RAB31 > TNPO2 > OBSCN > IRAK3 > LIN9 > SEC16B." (PMID 34359748, 2021). "By inducing the PI3K/AKT pathway, Rab31 was shown to promote tumour cell growth and reduce apoptosis." (PMID 34401050, 2021). "The small GTP-binding protein Rab31 plays an important role in the modulation of tumor biological-relevant processes, including cell proliferation, adhesion, and invasion." (PMID 34906074, 2021).
tumor (continued). "All in all, it seems reasonable that elevated Rab31 levels mediate anti-EMT-like activities which promote initial primary tumor growth as well as re-establishment of metastases at a distant site." (PMID 34906074, 2021). "Although various pathways have been proposed for Rab31-induced cell proliferation, the exact mechanism of how Rab31 modulates tumor growth remains elusive." (PMID 34906074, 2021). "The effects of Rab31 overexpression were analyzed in a 3D spheroid model, which more closely mimics the in vivo tumor microenvironment compared to classical 2D cell monolayer cultures." (PMID 34906074, 2021). "Immunofluorescence staining of normal mucosa and paired tumor tissue showed that RAB31 was highly expressed in goblet cells with dispersed cluster-like distribution in the cytoplasm." (PMID 33072555, 2020). "Our study mainly focused on RAB31 in CAFs; however, the tumor stroma consists of a variety of cells including macrophages, lymphocytes, and epithelial cells." (PMID 33072555, 2020). "In invasive tumour lines at least, high levels of Rab31 appear therefore to switch these cells from an invasive to a more proliferative phenotype." (PMID 25472813, 2015). "The impact of rab31 overexpression on tumor cell proliferation was analyzed by manual cell enumeration." (PMID 22920728, 2012). "Batch-transfected cells as well as selected cell clones, expressing different levels of rab31 protein, were analyzed with regard to proliferation, cell adhesion, the invasive capacity of tumor cells, and in vivo in a xenograft tumor model." (PMID 22920728, 2012). "In the present study, we aimed to investigate the impact of rab31 (over)-expression on important aspects of tumor progression in vitro and in vivo." (PMID 22920728, 2012). "Rab31 immunostaining was mainly observed in the cytoplasm of tumor cells with occasional perinuclear/nuclear staining." (PMID 22920728, 2012). "In vivo, Cx43 promoted tumor growth and modulated Rab31/autophagy pathways." (PMID 41463174, 2025). "However, our current findings demonstrate a paradoxical pro-autophagic role of Cx43 in TNBC, where it upregulates Rab31 to enhance autophagy and promote tumor progression." (PMID 41463174, 2025). "In addition, knockdown of Rab31 impairs tumor growth and metastasis through MAPK6 in a xenograft mouse model." (PMID 38695990, 2024). "Our results revealed that Rab31 promotes tumor metastasis and cisplatin resistance in STAD through Twist1-mediated EMT, which suggests that Rab31/Stat3/MUC-1/Twist1 pathway is a promising therapeutic target to overcome resistance to cisplatin and metastasis in STAD." (PMID 36781842, 2023). "Rab31 expression was significantly elevated in STAD tumor tissues compared with normal tissues." (PMID 36781842, 2023). "Rab31 was significantly upregulated in tumor tissues compared to adjacent normal tissues." (PMID 36781842, 2023). "Treatment with cisplatin along with Rab31 siRNA conferred the highest inhibition on tumor growth." (PMID 36781842, 2023). "Rab31 knockdown significantly inhibited the growth of tumors, as shown by the tumor growth curve." (PMID 34975321, 2022). "Its impact on TGF-ß expression in the primary tumor or in the distant metastases resulting in tumor growth may explain why high Rab31 levels in tumor tissue are related to poor patient prognosis." (PMID 34906074, 2021). "Consistently, it was reported that the migration of CRC cells could be promoted by the Ras-related protein Rab-31 (RAB31) through regulating HGF secretion in the tumor stroma." (PMID 34660589, 2021). "In colon cancer, increased Rab31 expression may promote tumor progression by regulating HGF secretion in the tumor stroma." (PMID 34141705, 2021). "Because HER2, IGF1R, MET and NTRK2 are also present in tumor-derived exosomes that play important roles in tumor progression, we aimed to investigate whether RAB31 control these RTKs entry into CD63-positive MVEs." (PMID 32958903, 2021).
tumor (continued). "Repression of TGF-ß by Rab31 overexpression may be part of the later mechanism to dampen the tumor-suppressing activities of the TGF-ß pathway." (PMID 34906074, 2021). "It is possible that RAB31 expressed in other cell populations may also affect the biological properties of CRC tumor cells." (PMID 33072555, 2020). "The expression level of Rab31 mRNA was similar in tumor and normal tissue." (PMID 31083279, 2019). "Using proliferation, adhesion, and invasion assays, we first characterized the phenotype of the cell transfectants with different rab31 expression levels in vitro, and then monitored the impact of rab31 expression on experimental metastasis in a xenograft tumor model in mice." (PMID 22920728, 2012). "Previous studies suggested Rab31 may influence tumor progression via autophagy." (PMID 41463174, 2025). "Furthermore, Rab31 knockdown impaired tumor growth and metastasis via MAPK6 in vivo." (PMID 34975321, 2022). "Besides, other Rab GTPases, such Rab1a and Rab31 have also been reported to affect mTOR pathway in tumor, but it is unclear whether these effects are achieved by the membrane transport of Rab GTPases." (PMID 34141705, 2021). "Therefore, increased RAB31 expression in the tumor stromal may be induced by specific factors in the microenvironment or may mark a specific subtype of CAFs." (PMID 33072555, 2020). "Rab31's modulation of EGFR trafficking – could it be tumour suppressive?" (PMID 25472813, 2015). "First, we restored the expression of RAB31 in BGC-823 cells transfected with miR-378a-3p mimics, and observed that the tumor suppressive effects of miR-378a-3p were partially reversed." (PMID 36245214, 2022). "Sodium selenite treatment upregulated pro-apoptotic, apoptotic, and tumor suppressor genes such as ATF3, FOSB, GADD45B, DUSP8 and ACHE, and downregulated tumor cell survival genes such as SCD, LRP1, RAB31, SRPX2, PDK1 and CSGALNACT1." (PMID 36059619, 2022). "CIMP status was predicted using an established array-based marker panel of CIMP, including B3GAT2, FOXL2, KCNK13, RAB31, and SLIT1, that was shown to identify CIMP+ (CIMP-H or CIMP-L) tumours with 100% sensitivity and 95.5% specificity, with 2.4% misclassification." (PMID 27846243, 2016).
RAB31 also shares sentences with these, for which no sentence is quoted: astrocytoma (2 papers); infection (2); actinic keratosis (1); Autoimmunity (1); esophageal SCC (1); Kawasaki disease (1); liver cancer (1); malignant brain tumor (1); Parkinson disease (1); Stomach Cancers (1); thyroid disease (1).